EGFL7 (EGF like domain multiple 7)
Diseases named in the same sentence as EGFL7 in open-access papers (continued):
Sharing a sentence is not in itself a finding about the gene and the disease.
cancer (continued). "These ambiguous results indicate that EGFL7 expression in human cancer needs to be carefully analyzed as EGFL7 may play a complex role in cancer biology depending on cancer origin and the source of EGFL7 secretion: cancer cells, endothelium or both." (PMID 35630004, 2022). "The results showed that EGFL6 and EGFL7 had a worse prognosis in these cancers." (PMID 33391349, 2020). "We found that 30 of these genes which included Nckap1l, Ncf1, Pla2g15, Unc93b1, Lrrc33, Rgs10, Gmfg, Rbm25, C3ar1, Ccdc88b, Fam105a, Gng11, Phc1, Rasa4, Dag1, Tyrobp, Tmsb4x, Cfp, Prkd1, Gp49a, Trem2, C1qc, Lyz2, Igfbp7, Rab30, Cxcl16, Egfl7, Ube2r2, Pltp, and Cfb, showed a relation with cancer." (PMID 32812032, 2020). "EGFL7 plays a vital role in controlling vascular angiogenesis during embryogenesis, organogenesis, and maintaining skeletal homeostasis, its dysregulation has been frequently found in several types of cancers." (PMID 32812032, 2020). "Similarly, miR-126/miR-126* was down-regulated by promoter methylation of its EGF-like domain multiple 7 (EGFL7) host gene in cancer cells." (PMID 31683635, 2019). "The expression of EGFL7 is primarily restricted to endothelial cells with a very limited expression in most other human tissues; however, under pathological conditions such as cancer, many tumors cells are known to secrete EGFL7 in order to promote angiogenesis." (PMID 29416688, 2018). "EGFL7 also has been shown to promote angiogenesis in a variety of cancers." (PMID 29416688, 2018). "Recent evidence focuses on the pro-angiogenic role of EGFL7 in cancer." (PMID 28983240, 2017). "Both studies thus demonstrated elevated cir-EGFL7 in the presence of cancer." (PMID 28539619, 2017). "However, it should be noted that expression of EGFL7 has been reported by others in cancer cells and neurons." (PMID 25592646, 2015). "The EGFL7 immunoperoxidase staining showed an intense staining of EC, but also faint signals in other cell populations, including adipocytes, smooth muscle cells, cancer cells and enteric neuronal cells." (PMID 25592646, 2015). "The EGFL7 immunoperoxidase resulted in intense staining of ECs (cytoplasm and cell membrane), and rather faint signals in smooth muscle cells, adipocytes, enteric neurons and sometimes cancer cells." (PMID 25592646, 2015). "Therefore, EGFL7 is a candidate predictive factor for cancer progression and metastasis." (PMID 24945379, 2014). "MiR-126 alters the biological functions of some genes such as PI3K, EGFL7, HOXA9, sKRAS, CRK, ADAM9, IRS-1, SOX-2, SLC7A5, and VEGF, as well as involves in inflammation, cell migration, angiogenesis, recurrence of cancer, and metastasis." (PMID 38445462, 2024). "During third phase, the activated EGFL7/NOTCH signaling maintains low level of c-Myc expression and gradually counters killing effect of EGFR kinase inhibition, and cancer cells are transitioning to drug-tolerant persister cells." (PMID 36309484, 2022). "The expression levels of EGFL8 were relatively lower among all cancer types than that of EGFL6 and EGFL7, with EGFL7 having the highest level of expression." (PMID 33391349, 2020). "A previous study reported that the effects of EGFL7 are mediated by the EGFR signaling pathway, which is critical for controlling cancer cell motility." (PMID 24945379, 2014). ", among them the correlated expression of mir-126/EGFL7 and that of mir-342/EVL have been shown to play important roles in gene regulation of cancers." (PMID 19435500, 2009). "No matter EGFL7 was expressed in cancer epithelium, endothelium or in both, it had no impact on OS (p = 0.761, p = 0.849, p = 0.995, respectively)." (PMID 35630004, 2022). "To assess the potential impact of EGFL7 on diapedesis we decided to compare intraepithelial immune infiltrates between tumors having EGFL7 activated in cancer nests and/or adjacent vessels and those without EGFL7 activation." (PMID 35630004, 2022).
cancer (continued). "A similar scenario was observed in MM where cancer tissue and its adjacent non-malignant (NM) counterpart were analyzed for the methylation status of the EGFL7 S2 promoter region in relation to miR-126 and EGFL7 expression." (PMID 31850200, 2019). "The epithelial–mesenchymal transition (EMT) initiates the metastatic cascade and endows cancer cells with invasive and migratory capacity; however, it is not known if EGFL7 promotes metastasis by triggering EMT." (PMID 24945379, 2014). "Although CASZ1 was reported to modulate EGFL7/RhoA pathway and pRb activity in different cell types, however, given the context-dependent function of CASZ1 in various cancers, we speculated that CASZ1 may have a different mechanism to counteract HCC growth and metastasis." (PMID 29506567, 2018). "EGFL7 expression in cancer cells was observed in 6/47 (12.77%) ICAM-1-positive and in 3/12 (25.00%) ICAM-1-negative tumors; ICAM-1 scores were also similar whether EGFL7 was expressed or not." (PMID 35630004, 2022).
infection (4 papers, 2017 to 2024). The state of being infected such as from the introduction of a foreign agent such as serum, vaccine, antigenic substance or organism. "Our findings revealed that the levels of Gata2, Fat4 and Pkd1, which are related to cell polarization, as well as Egfl7, Nrp1 and Foxc2, which are related to valve development, were downregulated after infection." (PMID 38638427, 2024). "Purified KSHV virions were used for infecting the HUVECs and the cells from 72 hours post-infection (hpi) and mock infection were collected for the detection of EGFL7 levels." (PMID 29416688, 2018). "T. annulata-infection of B cells and macrophages results in increased levels of miR-126-5p, while miR-126-3p levels remain low (right), despite both EGFL7 and pre-miR-126 being equivalently expressed in virulent and attenuated macrophages." (PMID 29570727, 2018). "We also tested the levels of EGFL7 during de novo infection of KSHV into the target cells, HUVEC (human unbilical vein endothelial cells)." (PMID 29416688, 2018). "Effective infection in vivo was verified by the detection of virus-encoded EGFP and anti-EGFL7 IF staining." (PMID 28656980, 2017).
adenocarcinoma (2 papers, 2014 to 2022). A common cancer characterized by the presence of malignant glandular cells. "We observed that EGFL7 knockdown in normally high EGFL7-expressing BGC823 cells (a poorly differentiated adenocarcinoma line) resulted in a change from the typical spindle-shaped mesenchymal cell morphology to an epithelial cell-like morphology (a sign of MET)." (PMID 24945379, 2014).
neurodegenerative disease (2 papers, 2023 to 2024). A disorder of the central nervous system characterized by gradual and progressive loss of neural tissue and neurologic function. "Further research on Egfl7 could uncover new therapeutic targets and improve outcomes for patients with neurodegenerative diseases, making it an exciting area of study in the field of lymphatics biology." (PMID 39013903, 2024).
vasculopathy (2 papers, 2019 to 2020). "EGFL7 can exert pro-angiogenic effects both in early disease and at later stages when vasculopathy is more prominent." (PMID 30872612, 2019). "We conclude that EGFL7 and its specific microRNA miR-126 may be involved in the pathogenesis of SSc vasculopathy and fibrosis." (PMID 30872612, 2019). "In early SSc we propose that EGFL7 plays a pro-angiogenic role suppressing vasculopathy which then increases at later stages when EGFL7 is absent for example in LSS dcSSc." (PMID 30872612, 2019).
EGFL7 also shares sentences with these, for which no sentence is quoted: clear cell renal cell carcinoma (2 papers); COVID-19 (2); liver cancer (2); malignant pleural mesothelioma (2); Allergy (1); benign tumor (1); biliary atresia (1); bone sarcoma (1); cervical cancer (1); granulosa cell tumor (1); hemangioendothelioma (1); hypertrophy (1); liver cirrhosis (1); multiple sclerosis (1); non-small cell lung carcinoma (1); pulmonary fibrosis (1); Pulmonary hypoplasia (1); squamous cell carcinoma (1); T-cell acute lymphoblastic leukemia (1); ulcerative colitis (1).